TLR4 (toll like receptor 4)
Diseases named in the same sentence as TLR4 in open-access papers (continued):
Sharing a sentence is not in itself a finding about the gene and the disease.
myocarditis (continued). "TLR4-mediated production of pro-inflammatory cytokines is also involved in different types of myocardial inflammation, and a number of trials evaluated TLR4 as a potential target for improvement of disease outcome and severity." (PMID 36678520, 2022). "Previously we reported that CD11b, TLR4, caspase-1, and IL-1β were increased by testosterone in male mice with myocarditis." (PMID 36741845, 2022). "TLR4 induction significantly increased the level of myocarditis 14 days after infection compared with WT mice." (PMID 35163412, 2022). "In cardiometabolic patients, myocardial inflammation is maintained by innate immune cell activation mediated by pattern recognition receptors such as Toll-like receptor 4 (TLR4) and downstream activation of the NLRP3 inflammasome and NF-κB-dependent pathways." (PMID 34671656, 2021). "More specifically, infiltration of leukocytes (CD45), lymphocytes (CD3) and macrophages (Mac3) decreased in the absence of OGN, supporting the pro-inflammatory role of OGN in myocarditis through enhanced TLR4 signaling." (PMID 27878326, 2017). "Current evidence has demonstrated that the host immune response and inflammation mainly mediate myocarditis, where TLR4 participates in the induction of pro-inflammatory and antiviral cytokines." (PMID 27228349, 2016). "In contrast, patients with acute myocardial inflammation, TLR4 were more expressed on circulating CD14+CD16+ monocytes than on CD14+CD16- monocytes." (PMID 24499354, 2014). "The role of TLR4 in the pathogenesis of CB3 virus-induced myocarditis demonstrated that signaling through multiple receptor pathways is necessary for a cytokine environment that exaggerates viral replication and heart tissue damage." (PMID 24586934, 2014). "Further evidence for the role of TLR2 and TLR4 in CVB3 myocarditis was obtained by treating male and female C57Bl/6 mice with either 50μg PAM3CSK4 (PAM; TLR2 agonist) or 20 mg/kg Ultra-Pure LPS (UP-LPS; TLR4 agonist)." (PMID 23241283, 2012). "While microarray analysis showed sex differences in TLR2 expression, a role for TLR4 in CVB3 myocarditis has also been shown." (PMID 23241283, 2012). "TLR4 mRNA was reportedly increased in endomyocardial biopsy samples from patients with clinically suspected myocarditis and from those with idiopathic dilated cardiomyopathy." (PMID 21977329, 2011). "In a mouse model of EAM, Nishikubo and colleagues demonstrated that TLR4-induced Th1 immune response was required for the development of myocarditis induced by myosin and BCG." (PMID 21977329, 2011). "In an animal model of myocarditis, investigators found that TLR4 and IL-12 receptor β1 exacerbated coxsackievirus replication and myocarditis, whereas IFN-γ protected against viral replication." (PMID 21977329, 2011). "Our findings demonstrate that miR-93-3p directly targets 3′UTR of EIF4EBP1, consistent with prior studies showing that miR-93-3p alleviates renal injury by targeting NFAT5, promotes cellular proliferation and migration via targeting ZFP36L1, and modulates myocarditis by regulating TLR4 expression." (PMID 40900833, 2025). "EVs that contain replicative virus and/or virus particles and mitochondrial components may form powerful danger signals to the immune system activating TLR4- a key pathway in the pathogenesis of myocarditis and DCM." (PMID 38550582, 2024). "Studies in mouse models of coxsackievirus infection have shown that testosterone promotes TLR4 signalling in myocarditis, which might contribute to increased levels of IL-1β and IL-18, leading to cardiomyocyte apoptosis and contractile dysfunction." (PMID 38681683, 2024). "Indeed, generally, androgens have been found to increase Th1 responses and, in acute myocarditis, testosterone promotes the pro-inflammatory Th1 and/or Th17-type immune response and increases the activity of the inflammasome and TLR4 signaling pathways." (PMID 37112659, 2023). "One of the main pathway involved in myocarditis is the TLR4/NF-κB pathway." (PMID 37627502, 2023).
myocarditis (continued). "CVB3-induced myocarditis was mediated by TLR4 overexpression in AKT KO mice." (PMID 35163412, 2022). "Excessive activation of TLR4/IRAK1/TRAF6/NF-κB pathway commonly exists in myocardial inflammation." (PMID 36148071, 2022). "We previously showed that TN-C provides DCs to induce myocarditis via TLR4 activation." (PMID 33692798, 2021). "Previous studies have demonstrated that the Toll-like receptor 4 (TLR4)/nuclear factor-κB (NF-κB) signaling pathway not only plays a critical role in MI-induced myocardial inflammation but also is involved in the NLRP3 inflammasome-mediated inflammatory response." (PMID 34512865, 2021). "TN-C-stimulated BMDCs from TLR4-deficient mice failed to induce myocarditis in the recipients, indicating that TN-C provides myocarditis inducibility to DCs, at least in part, via TLR4 interaction." (PMID 33692798, 2021). "In this study we found that exposure to BPA in drinking water elevated proinflammatory cytokines/ receptors in the heart of female mice during CVB3 myocarditis that would typically be elevated in male mice or men with mycarditis such as TLR4, caspase-1, IL-1β, IL-17A, and IFNγ." (PMID 31551929, 2019). "They found that the severity of myocarditis, degree of viral replication, and levels of IL-1β/IL-18 expression were significantly reduced in TLR4-deficient mice and that TLR4 as well as IL-12Rβ1 aggravated CVB3 infection and myocarditis but IFN-γ inhibited viral replication." (PMID 29854842, 2018). "Finally, we highlight the involvement of TLR4 in myocardial inflammation, including myocarditis, MI, and I/R injury, and the clinical prospective of TLR4 inhibition." (PMID 27228349, 2016). "The underlying mechanism may involve the altered composition and structure of TLR4 ectodomain by the Asp299Gly polymorphism, leading to a decrease in the interaction of TLR4 with DAMPs and thereby attenuated TLR4-mediated myocardial inflammation." (PMID 27228349, 2016). "TLR4 can also play a beneficial role in myocardial inflammation, especially in myocarditis." (PMID 27228349, 2016). "The levels of TLR4 mRNA and protein have been found to be increased in murine hearts after myocardial ischemic injury, and in human hearts derived from patients with dilated cardiomyopathy and myocarditis." (PMID 23388509, 2013). "Therefore, TLR4 contributes significantly to the pathogenesis of SARS-CoV-2, and its overactivation causes a prolonged or excessive innate immune response and produces not only myocarditis but also multiple organ injury." (PMID 36498573, 2022). "Indeed, inhibiting TLR4 might be contraindicated in myocarditis due to its essential function in inducing increased CXCL1/KC protein expression in the course of myocarditis." (PMID 24586934, 2014). "Furthermore, as early as 6 h-12 h after infection mast cells and macrophages obtained from the spleen or peritoneum of males express more TLR4 than females, displaying the same innate immunological profile in the spleen as observed in the heart during acute myocarditis." (PMID 21338512, 2011). "Activation of TLR4, NLRP3 and IL-1β in gout are known factors that drive the pathogenesis of myocarditis." (PMID 38464847, 2024). "Based on these results, astragalus polysaccharides have been shown to protect TLR4-induced myocardial injury and inflammation by inhibiting the CVB3-related signaling pathway, which provides a potential target to treat myocarditis." (PMID 35514979, 2022). "TLR4, the first TLR to be found in human beings, has been reported to perform a variety of functions in a number of pathological conditions, including myocarditis, and its level in the heart is the highest compared with other TLRs." (PMID 29854842, 2018). "At the chronic stages of myocarditis (28 days pi CVB3) only Tlr2, Tlr4 and Tlr6 showed still an increased gene expression." (PMID 29538462, 2018).
myocarditis (continued). "Although the mechanism has not yet been elucidated, the difference in cardiac function and survival/HF between TLR3- and TRIF-deficient mice suggests that TLR4-mediated TRIF may be responsible for reducing the negative cardiac effects of IL-33 in the heart during acute CVB3 myocarditis." (PMID 22013485, 2012). "Remarkably, all the miRs in PEV were reported in the literature to be anti-viral, anti-inflammatory, to inhibit the TLR4/inflammasome pathway, or had been shown to decrease CVB3 myocarditis in an animal model, which correlates to the global shut-down of myocardial inflammation observed for PEV." (PMID 39835120, 2024). "Although IFNγ is increased in our model of CVB3 myocarditis in males, we showed that elevated IFN levels in male BALB/c mice with myocarditis are mediated by IL-18, which is downstream from TLR4, rather than traditional STAT4/IL-12 transcriptional activity." (PMID 39696682, 2024). "Immunostaining for TLR4 showed an overexpression of TLR4 in PS patients vs. no-PS myocarditis and vs. controls (3.44 ± 0.51 vs. 1.56 ± 0.2 and 3.44 ± 0.51 vs. 0.18 ± 0.17)." (PMID 37373705, 2023). "Since in both EAM models the activation of heart pathogenic T cells is independent of functional TLR4, it is not surprising that C3H/HeJ develop BCG-porcine myosin induced myocarditis after blocking IL-4." (PMID 24586934, 2014). "Semiquantitative evaluation of immunostaining (grades from 0 to 4) for IL-17A and TLR4 showed an increased cardiomyocyte expression of IL-17A in PS myocarditis compared with no-psoriatic patients and vs. controls (respectively, 3.95 ± 0.13 vs. 1.91 ± 0.5 and 3.95 ± 0.13 vs. 0.19 ± 0.2)." (PMID 37373705, 2023). "TLR4 and IL-12Rβ1 might share common downstream pathways that directly affected IL-1β and IL-18 production, and IL-1beta and IL-18 played an important part in the pathogenesis of CVB3-induced myocarditis." (PMID 29854842, 2018). "The observation of TLR4 aggravation of myocarditis in males is not unexpected as studies by Fairweather and colleagues have previously shown that TLR4 expression is significantly increased in CVB3 infected male BALB/c mice and that blocking TLR4 reduces myocarditis." (PMID 23241283, 2012). "Myocarditis-NCV was classified as immune-mediated when anti-heart Abs were positive, viruses in cardiac tissue were absent, myocardial TLR-4 was overexpressed and inflammatory cytokines (IL-1β, IL-6, IL-8, TNF-α) in serum samples were elevated." (PMID 33355356, 2021). "It is remarkable that all cases with immune-mediated Myocarditis-NCV were virus-negative at myocardial PCR, had positive anti-heart Abs with partially organ-specific pattern, and showed overexpression of TLR4 at tissue immunohistochemistry." (PMID 33355356, 2021).
endometriosis (53 papers, 2008 to 2026). The growth of functional endometrial tissue in anatomic sites outside the uterine body. "The detection of bacteria such as Escherichia coli in menstrual blood further supports the concept that both exogenous and endogenous ligands can activate TLR4 pathways, thereby exacerbating the inflammatory responses associated with endometriosis." (PMID 40862752, 2025). "One study assessed the diagnostic performance of high mobility group box-1 (HMGB1) and toll-like receptor 4 (TLR4), which seem to be associated with this process of damage-associated molecular patterns (DAMPs) and induce endometriosis." (PMID 38337827, 2024). "The TLR4 cascade is directly linked to the growth and progression of endometriosis lesions and subsequent pelvic inflammation." (PMID 39596309, 2024). "In the present study, we used a case-control approach to assess if TLR4 T399I polymorphism is a susceptibility factor to endometriosis in Italian women." (PMID 32349318, 2020). "In conclusion, our data indicate the association of the TLR4 rs4986791 T allele with endometriosis in an Italian cohort of women, this supporting the role of genetic variations in the modulation of the TLR4-mediated immune response in endometriosis disease." (PMID 32349318, 2020). "Altogether, our results indicate that the presence of the TLR4 rs4986791 T variant may be considered a genetic risk factor for endometriosis." (PMID 32349318, 2020). "This study investigates the role of the TLR4/NF-κB/NLRP3 inflammasome axis in endometriosis pathogenesis and evaluates the therapeutic potential of pharmacologic TLR4 inhibition." (PMID 42123727, 2026). "Altered TLR4 expression has also been documented in various immune cell populations within the peritoneal cavity of women with endometriosis, highlighting immune dysfunctions that support chronic inflammation." (PMID 40862752, 2025). "In particular, TLR4 has garnered considerable attention for its significant involvement in the pathophysiology of endometriosis." (PMID 40862752, 2025). "In a mouse model of endometriosis, ASIV was shown to suppress endometriosis-induced inflammatory lesions and attenuate TLR4/NF-ĸBsignaling activated in vivo in endometriosis." (PMID 40362487, 2025). "Drawing insights, we propose that endometriosis progression involves TLR4/NF-κB, Wnt/frizzled signaling pathways, and estrogen receptors—promising targets for both therapeutic interventions and diagnostic approaches." (PMID 39108650, 2024). "LPS can work through the classic toll-like receptor signaling pathway, which has been shown to promote the occurrence and progression of endometriosis via binding with Toll-like receptor 4 (TLR4)." (PMID 38505548, 2024). "Their study revealed that E. coli LPS contributes to regulating pelvic pro-inflammatory responses and the progression of endometriosis through the LPS/TLR4 cascade." (PMID 38961459, 2024). "In response to multiple factors such as IL-1β, TNF-α, and TLR4, endometriotic cells activate the NF-κB signaling pathway, affecting endometriosis initiation and progression." (PMID 36769226, 2023). "Lipopolysaccharide (LPS) is a component of the outer membrane of Gram-negative bacteria and regulates the uncontrolled activation of inflammatory and immune responses in the pelvis and the growth of endometriosis via the LPS/TLR4 cascade." (PMID 36744089, 2023). "TLR4 is expressed by various immune cells and has been found to be higher in endometrial stromal cells of endometriosis patients." (PMID 37446108, 2023). "Another compound with anti-inflammatory action in endometriosis is astragaloside IV, produced by Astragalus membranaceus by inhibition of the TLR4/NF-κB pathway." (PMID 36769226, 2023). "This study aimed to elucidate the possible mechanism of Bushen Wenyang Huayu Decoction (BWHD) in treating endometriosis (EMs) by targeting TLR4/NF-κB-mediated autophagy." (PMID 36437825, 2022).
endometriosis (continued). "Based on these results, we suggest that TLR4/NF-κB and Wnt/frizzled signaling pathways, as well as estrogen receptors, regulate the progression of endometriosis." (PMID 36339397, 2022). "The TLR4 D299G SNP has been previously investigated in endometriosis, in Indian and Brazilian cohorts of women." (PMID 32349318, 2020). "Differential expression of antiinflammatory cytokines (IL-10, TGF-β, TLR4 and NF-κB) occurs in women with endometriosis, and this can promote survival, growth, invasion, differentiation, angiogenesis, and immune escape of the endometriotic lesions." (PMID 32210799, 2020). "In endometriosis patients, a significant increase in TLR4 mRNA expression in ectopic endometriotic lesions compared with corresponding eutopic tissue was reported." (PMID 32349318, 2020). "Authors hypothesized that in women carrying the TLR4 D299G polymorphism, particularly during the period of menstruation, the retrogradely shed endometrial cells could be implanted on the peritoneum (in the pouch of Douglas) and favorite the onset of endometriosis." (PMID 32349318, 2020). "Among these, Toll-like receptor 4 (TLR4) represents a good candidate due to its role in the immune/inflammatory response and endometriosis pathogenesis." (PMID 32349318, 2020). "Because LPS binds to TLR4 and activates MyD88 signaling, the current findings using Myd88−/− mice are consistent with LPS actions in endometriosis." (PMID 31507610, 2019). "Analysis of TLR4 expression has also supported that the pathological endometrium affects the development of endometriosis." (PMID 26872033, 2016). "We propose that the sterile inflammation process, which occurs in the pelvic cavity upon endometriosis, is able to enhance the epithelial TLR4 expression and thus activate the known downstream signalling cascade." (PMID 18775079, 2008). "Our data suggest an involvement of TLR3 and TLR4 in endometrial diseases as demonstrated by altered expression levels in endometriosis and endometrial cancer." (PMID 18775079, 2008). "Our data suggest an involvement of TLR3 and TLR4 in endometrial diseases as we demonstrated altered expression levels for both receptors in endometriosis and endometrial adenocarcinoma." (PMID 18775079, 2008). "Concerning protein localization, we found TLR3 and TLR4 proteins in glandular and epithelial cells of endometriosis patients." (PMID 18775079, 2008). "The TLR4/NF-κB/NLRP3 axis may drive endometriosis progression by linking innate immunity, inflammasome activation, pyroptosis, with possible involvement in angiogenesis warranting further investigation." (PMID 42123727, 2026). "Furthermore, CD4 + TLR4 in the comparison of PE vs. CC (AUC = 0.86) confirms the role of this receptor in more advanced forms of endometriosis." (PMID 40862752, 2025). "Interestingly, a study from Japan revealed that TLR4 mediated the oxidative stress and inflammatory burden in endometriosis by analyzing the endometrial tissues." (PMID 38539234, 2024). "This indicates that as an initial inflammatory mediator, LPS could be involved in pelvic inflammation and promote the TLR4/ NF-κB mediated growth of endometriosis." (PMID 38505548, 2024). "Elevated LPS levels in peritoneal fluid may promote Toll-like receptor 4 (TLR4)-mediated progression of endometriosis." (PMID 38938880, 2024). "Additionally, a study in mice showed that LPS, by generating peritoneal inflammation through activation of the TLR4/NF-κB pathway, exacerbated the development of endometriosis-like lesions." (PMID 37446108, 2023). "Animal experiments have demonstrated that activation of the LPS/TLR4 pathway, induced by injecting lipopolysaccharide (LPS) into a mouse model of endometriosis, leads to the release of inflammatory factors and promotes the proliferation and invasion of ectopic endometrial stromal cells." (PMID 37446108, 2023).